RN7SKP133 (RN7SK pseudogene 133)
Gene: Miscellaneous RNA gene on chromosome 5 (17,345,616 to 17,345,955, forward strand). Ensembl gene ENSG00000201715.
Homologues: Orthologues: chimpanzee 7SK (97% identical). Paralogues in human: RN7SKP9 (72% identical), 7SK (72% identical), RN7SKP124 (71% identical), RN7SKP180 (71% identical), RN7SKP184 (71% identical), RN7SKP203 (71% identical), RN7SKP217 (71% identical), RN7SKP71 (71% identical), RN7SKP230 (70% identical), RN7SKP79 (70% identical), RN7SKP162 (70% identical), RN7SKP176 (69% identical), and 284 more.